BAP1 (BRCA1 associated deubiquitinase 1)
Diseases named in the same sentence as BAP1 in open-access papers (continued):
Sharing a sentence is not in itself a finding about the gene and the disease.
cancer (continued). "The overall prevalence of cancer was significantly higher in the BAP1-mutated cohort compared with the non-mutated cohort (63.5% and 9.1% respectively, p < 0.001)." (PMID 22935333, 2012). "To avoid the overestimation of the cancer risks estimates usually due to publication bias in meta-analyses, we chose to compare BAP1 mutated vs non-mutated patients from the same families." (PMID 22935333, 2012). "However, additional cancers are found more rarely in BAP1-TPDS patients." (PMID 41670784, 2026). "Other cancer germline mutations, such as BAP1, BRCA1, or BRCA2, were negative." (PMID 40283643, 2025). "There were no other cancer-related germline mutations, including BAP1, BRCA1, or BRCA2." (PMID 40283643, 2025). "Thus, the role of BAP1 in cancer development is controversial." (PMID 39984455, 2025). "However, treatments for metastatic BAP1-mutant cancers are limited." (PMID 40754831, 2025). "In addition, UMRC-6 cells reconstituted with BAP1 mutants found in cancer patients indicate that only the wild-type BAP1 is able to induce autophagy, therefore, suggesting that all clinically relevant BAP1 mutations analyzed behave as loss-of-function in their ability to modulate autophagy." (PMID 40754831, 2025). "Thus, it is not surprising that human BAP1 mutations predispose to cancer and global Bap1 knockout causes early embryonic lethality in mice." (PMID 38690732, 2024). "A protein called BAP1, which removes tags marking proteins for degradation, is an important guardian of genome stability, and understanding its function may help in developing cancer therapies." (PMID 37009801, 2023). "Furthermore, our data that BAP1 inactivation, which is a frequent event in this cancer, can interfere with SAC activity and spindle organization may confer resistance to vinorelbine and this is being explored in the VIM trial." (PMID 36550359, 2023). "The role of BAP1 in DSB repair may provide a therapeutic window for BAP1-defective cancer." (PMID 37009801, 2023). "Therefore, the exact physiological and pathological role of BAP1 depend on cell or tissue context and cancer type which might be affected by the cell microenvironment." (PMID 37543638, 2023). "Intriguingly BAP1w-/KO MeT5A cells largely recapitulate these cancer-associated expression changes suggesting BAP1 mutation may be sufficient, although not required, for adaptation." (PMID 36669126, 2023). "Thus, it is of great interest to develop small molecules and PROTACS that would either specifically target a discrete PRC1 complex or at least discriminate between cPRC1 and vPRC1 complexes, particularly in the context of cancers with high levels of H2AK119ub1, like BAP1 mutant tumors." (PMID 36105358, 2022). "The BAP1 mutation-specific miRNA signature has previously been identified as prognostic biomarkers in other cancers as well whilst BAP1 alone could not be correlated with clinical outcomes." (PMID 36012262, 2022). "Finally, we argue that in cancer development the maintenance of genomic integrity is a pivotal aspect of the pathogenesis and whether and BAP1 dependent regulation of the cellular epigenome impact the genomic integrity remain an eluded critical question." (PMID 36318367, 2022).
cancer (continued). "In conclusion, these results demonstrate that whereas many cells do not survive in the absence of Bap1 due to activation of the apoptotic pathway, Bap1 deletion does not cause apoptosis in some cancer-prone cells, such as melanocytes, but rather promotes carcinogenesis." (PMID 35874820, 2022). "However, BAP1 has also been reported to protect cancer cells against cell death." (PMID 33919439, 2021). "Therefore, BAP1 germline testing might be useful in case of familial UM or the occurrence of other cancers in a patient’s family history." (PMID 33396957, 2020). "Importantly, BAP1 is also known to be positivelyassociated with cancer progression." (PMID 32422649, 2020). "Moreover, synthetic lethal strategies have the unique benefit of enabling targeting of loss-of-function alterations, which would be relevant for cancer types frequently exhibiting reduced expression of E3 ubiquitin ligases (e.g., RNF20 or RNF40) or DUBs (e.g., BAP1 or USP22)." (PMID 30781493, 2019). "A particular challenge for mutation screening is the classification of non-truncating BAP1 sequence variants because it is not known whether these subtle changes can affect the protein function sufficiently to predispose to cancer development." (PMID 25830670, 2015). "We further extended this framework to five additional cancer-related genes (VHL, ATM, BRCA1, RAD51C, and BAP1), establishing a generalizable framework for gene-specific VEP with potential applications in precision medicine." (PMID 41955512, 2026). "Participants were asked about communication surrounding BAP1-TPDS with family members, and their current cancer surveillance." (PMID 41843333, 2026). "After observation of a radiologically malignant-appearing splenic mass with benign pathology in a patient with BAP1-TPDS, we sought to retrospectively characterize splenic lesions in individuals with BAP1-TPDS seen at a comprehensive cancer center." (PMID 38824259, 2024). "We characterize MBD5 and MBD6 as important regulators of the BAP1 complex and maintain its transcriptional landscape, shedding light on the therapeutic potential of targeting MBD5 and MBD6 in BAP1-dependent human cancers." (PMID 36180891, 2022). "Recent studies have shown that PR-DUB and the catalytic function of BAP1 are required for maintenance of PRC2 target gene occupancy and PcG-mediated repression in ESC and cancer cells." (PMID 36105358, 2022). "To determine the dependency of BAP1 in a broad panel of SCLC cell lines, we retrieved the genome-wide CRISPR screening and RNAi screening results in different SCLC cell lines from the Cancer Dependency Map (DepMap)." (PMID 35194152, 2022). "PPI of BAP1 with BRCA1 was central to understanding the role of BAP1 in growth-control pathways and cancer; BAP1 was suggested to play a role in BRCA1 stabilization." (PMID 33916178, 2021). "Since BAP1 loss-of-function sensitizes cells to DNA repair defects, the use of PARP inhibitors could be considered, especially in combination with or sequentially to therapies inducing double-strand DNA break, such as platinum-based chemotherapy, as observed in other cancer types." (PMID 33915954, 2021). "Through cancer genomic analyses, it was shown that SLC7A11 and BAP1 expression were inversely correlated in cancer." (PMID 33499222, 2021). "Intriguingly, here we identified that BAP1 served as a novel deubiquitinase of PTEN to control the PI3K‐Akt signaling pathway and cancer progression in PCa." (PMID 33155366, 2021). "Concerning additional cancer genes identified in the significantly altered regions, some were characterized as known drivers (SETD2, BAP1, FLT4 and PTEN) and others as predicted drivers (FGFR4 and NSD1), according to the CGI." (PMID 33668731, 2021).
cancer (continued). "Our screening procedure was robust as a subset of the highly ranked genes (BAX, BIM, BAP1, and SPRED2) had previously been correlated to either CML progression, imatinib resistance, or resistance to alternative therapies in different cancer types." (PMID 38831555, 2020). "Because of the strong link between BAP1 overexpression and ERG rearrangement, the analysis was repeated in the subsets of ERG-negative and ERG-positive cancers." (PMID 31903168, 2019). "In contrast to observations in other cancers, sensitivity to pharmacologic inhibition of EZH2 by GSK126 was decreased in the setting of reduced BAP1 expression." (PMID 28122578, 2017). "BAP1 was originally discovered as a binding partner for BRCA1 and shown to inhibit cancer cell growth." (PMID 29088836, 2017). "Several members of the DUB family are known to contribute to carcinogenesis, including USP1, USP2, USP7 and USP22, while other DUBs are down-regulated in human cancers, including USP10 and BAP1." (PMID 27030989, 2016). "During a 1-month period, BAP1 and KLF5 knockdown cancer cells grew significantly slower than the Lucsh control cells." (PMID 26419610, 2015). "Here, I will focus on the emerging roles of the H2A DUBs USP3, USP16, USP44, BAP1, and MYSM1 in HSC maintenance and cancer." (PMID 26442100, 2015). "In 12 individuals with UM and unknown family history of cancer, we found no BAP1 mutations." (PMID 25803691, 2015). "SETD2 and BAP1 both lie on the short arm of chromosome 3, undergo copy-neutral LOH or deletion and are driver genes for ccRCC and other cancer types." (PMID 25790038, 2015). "It is worth noting that although LOH in cases with BRCA1 and BRCA2 truncations mutations were largely restricted to OV and BRCA, the majority of LOH truncations in other genes (for example, ATM, PALB2, BAP1, FANCM) were found across cancer types." (PMID 26689913, 2015). "Mutations in these genes appear to be either specific to ICC, as is the case of IDH1 and IDH2 (p=0.0005), or cluster within this cancer type as is the case for ARID1A, BAP1, and PBRM1 that were found in 34.3% (24/70) of ICC." (PMID 24867389, 2014). "Our results reveal that germline BAP1 mutations cause a novel autosomal dominant hereditary cancer syndrome, the BAP1 cancer syndrome, characterized predominantly by MM, UVM, CM and by MBAITs and possibly by other cancers." (PMID 22935333, 2012). "BAP1 and MTAP genes are significantly involved in the development of cancer." (PMID 40506895, 2025). "All alteration types, regardless of cancer type, resulted in lower RNA-level expression of BAP1 than unaltered samples (two-sided pairwise Mann–Whitney U test with continuity correction P< 0.01 for each alteration type)." (PMID 39554490, 2024). "We identified 37 individuals with BAP1-TPDS, 81% with a history of cancer." (PMID 38824259, 2024). "Several clinical trials targeting BAP1 alterations in multiple cancer types (not OC) are ongoing (e.g. NCT03207347, NCT04666740, NCT03654833, NCT02925234)." (PMID 38519644, 2024). "Moreover, by using the same evaluation criteria, we identify new biomarkers whose impact on drug response spans multiple cancers, including SALL4, B2M, BAP1, CCDC6, ERBB4, FOXA1, GRIN2A, and PTPRT." (PMID 39083502, 2024). "DHFR and RRM1 are linked with sensitivity to therapeutics used in MPM, pemetrexed, and gemcitabine, respectively; however, they did not stratify by BAP1 status, implying more complex regulation of their expression in cancer." (PMID 36669126, 2023).
cancer (continued). "In this study, we found that focal adhesion was enhanced in shBAP1 cell samples and negative regulation of double strand break repair via nonhomologous end joining was enhanced in BAP1 high tissue samples, suggesting its cancer-inhibiting effect." (PMID 36003792, 2022). "Additionally, sufficient studies have suggested that SETD2, BAP1, mTOR, MUC16, HMCN1, KDM5C, ARID1A, and PTEN are intimately tied to prognosis and immune response in cancers." (PMID 35936012, 2022). "BAP1-mutant UMs display a suppressive TIME enriched for M2 polarized macrophages and T cells expressing checkpoint or “exhaustion” markers such as LAG3, TIM3, and TIGIT, similar to findings in other cancer types." (PMID 35954340, 2022). "Compared with other DUBs, such as BAP1 and USP7, OTUD3 is rarely studied in cancer." (PMID 34380780, 2021). "Conversely, knockdown of BAP1 in PCa cells leads to the decrease in PTEN protein level and the activation of the Akt signaling pathway, therefore promoting malignant transformation and cancer metastasis." (PMID 33155366, 2021). "BAP1-TPDS is highly penetrant, with ~85% of heterozygous carriers diagnosed with cancer." (PMID 33105797, 2020). "Furthermore, H2A deubiquitinases, such as BAP1, USP14 and USP28, have been shown to suppress proliferation and increase radiosensitization in human cancers." (PMID 31761786, 2019). "We show that CD47 is not modulated at different cancer stages, although patients with the lowest expression of CD47 show significant better progression-free survival, after correcting for the presence of BAP1, GNAQ, and GNA11 mutations." (PMID 31277366, 2019). "The substantially higher BAP1 expression in ERG positive (30% with strong BAP1 positivity) than in ERG negative cancers (12% with strong BAP1 positivity) provides strong in vivo evidence for an ERG-BAP1 interaction." (PMID 31903168, 2019). "From a diagnostic point of view, our work will help the clinicians to consider the role of the BAP1 gene expression in 29 cancer types, which were never discussed before." (PMID 31635116, 2019). "For instance, the BAP1 H2A deubiquitinase recruits H3K4 monomethylase MLL3 to monomethylate gene enhancers, while disruption of the interaction between BAP1 and MLL3 contributes to the pathogenesis of multiple cancers." (PMID 31747960, 2019). "The data on BAP1-TPDS was based on self-reported personal and family history of cancer." (PMID 30477459, 2018). "Few mutational studies have investigated the role of BAP1 in GBC, and no functional study in vitro-, or clinical studies about cancer survival have been done." (PMID 30395583, 2018). "MPM exhibits a distinct genomic signature, including inactivating mutations in cyclin-dependent kinase inhibitor 2A (CDKN2A), and more recently, ubiquitin carboxyl-terminal hydrolase (BAP1) and neurofibromin 2 (NF2), have been shown to be the most prevalent in this type of cancer." (PMID 29342862, 2018). "BAP1 has garnered attention for its links with cancer, however, the molecular mechanism in the regulation of cancer by BAP1 has not been established." (PMID 28935764, 2017). "Malignancies without BAP1 inactivation generally have a favourable prognosis because of their lower rates of visual morbidity and metastasis and a five-year mortality rate of 2%–3%." (PMID 28487752, 2017). "Alterations in chromatin modulators like the nuclear deubiquitinating enzyme BAP1 are the most frequently observed genetic alterations reported in intrahepatic CCA, yet the molecular mechanisms by which they modulate cancer cell behavior are unknown." (PMID 28122578, 2017).
cancer (continued). "In contrast to the TCGA-data, the ‘top 20’ list of ‘Cancer census genes’ most frequently involved in a copy number loss in the LP-WGS-data did not contain NF2, CDKN2A or BAP1." (PMID 29371938, 2017). "The Cancer Genome Atlas Research Network supports the fundamental role of oxygen-sensing genes (VHL) and chromatin remodeling genes (PBRM1, BAP1 and SETD2) in RCC tumorigenesis, highlighting their potential as prognostic biomarkers and/or future therapeutic targets." (PMID 26452128, 2015). "In light of the effect of transient BAP1 depletion on HDAC expression, we hypothesized that variation in the endogenous expression of BAP1 in cancer cells may also influence HDAC levels." (PMID 25970771, 2015). "Interestingly, this database shows that the BAP1 gene is significantly downregulated in cancer compared to non-adjacent normal tissues." (PMID 40136571, 2025). "The absence of BAP1 was observed in the UM cell lines, which was a feature of cancer aggression." (PMID 37710185, 2023). "In MPM cell lines, the LC50 ranged from 9.7 μmol/L to >1.2 mmol/L; however, mizoribine sensitivity appeared unrelated to ASS1 expression or BAP1 status, correlating most closely with proliferative capacity and suggesting MPM are biologically distinct from other ASS1-high cancers." (PMID 36669126, 2023). "However, as BAP1 molecular alterations have been detected also in cancer patients occupationally not-exposed to asbestos, further studies are needed to better clarify the role of BAP1 gene in asbestos-induced carcinogenesis." (PMID 35755315, 2022). "BAP1 also induces cell death in cancer cells independent of transcriptional regulation." (PMID 33919439, 2021). "Thus, we suspect that the novel interaction of BAP1 and PARP3 may also be perturbed by PARP inhibitors, leading to inhibition of cancer growth." (PMID 33916178, 2021). "That the impact of BAP1 on proliferation was much stronger in ERG negative than in ERG positive cancer further supports the notion that ERG activation may interfere with functions of BAP1." (PMID 31903168, 2019). "The results of this study suggest that BAP1 expression may represent a useful marker in ERG negative cancer." (PMID 31903168, 2019). "Since our hypothesis is that BAP1, PBRM1, KDM5C, SETD2 are critical to maintain the expression and/or function of ISGF3 subunits in the ccRCC cancer cells, we concluded that mRNA levels in the bulk tumors from the TCGA dataset are not suitable for our validation experiments." (PMID 30355451, 2018). "On the other hand, our data suggest that cancer cells develop compensatory mechanisms to survive without BAP1; identifying these mechanisms may provide new opportunities for synthetic lethal strategies." (PMID 25970771, 2015). "Therefore, cancer patients with low or absent antitumor immunity respond to immune checkpoint inhibitor treatment may benefit from the pharmacological inhibition of BAP1 activity." (PMID 39817454, 2025). "Interestingly, BAP1 and PSMD13 genetic alterations do not co-occur in any of the samples reported in these studies, suggesting that the presence of mutations in both genes compromise cell viability, not only in MPM, but also in BAP1-TPDS-related cancer types." (PMID 36980270, 2023). "In vitro tests on MP41 (BAP1 positive) and MP46 (BAP1 negative) cancer cell lines using inhibitors pamiparib (PARP1) and Ymu1 (DTYMK) demonstrated significant cytotoxic effects." (PMID 39195238, 2024). "Proteases present in malignant tumours but not in normal skin included: PGC, BAP1, caspase-8, F13A1, MMP11, MMP23, MMP25, MMP26 and granzyme-A." (PMID 35327667, 2022). "The carcinomas with BAP1 or MTAP loss included one adenocarcinoma with <80% EZH2 staining and negative CD117 staining, such that the addition of BAP1 and MTAP to a panel of EZH2 (≥80% threshold) and CD117 slightly increased the sensitivity for carcinoma from 92% to 95%." (PMID 37190202, 2023).
cancer (continued). "Besides targeting just histone substrates, BAP1 can also function as a deubiquitinase of non-histone proteins, such as HCFC1, KLF5, INO80, DNMT1, IP3R3, and PGC1-α, most of which have been reported as key regulators in human cancers." (PMID 35194152, 2022).